ALB (albumin)
Diseases named in the same sentence as ALB in open-access papers (continued):
Sharing a sentence is not in itself a finding about the gene and the disease.
malnutrition (continued). "Malnutrition (albumin < 36.0 g/L) modified the association between LDL-C and cardiovascular mortality (P for interaction = 0.01)." (PMID 35938138, 2022). "A low level of albumin implies the degradation of skeletal muscle protein, which also means that a person is at risk of malnutrition." (PMID 35453410, 2022). "It was revealed that the second most common cause of inappropriate albumin use in the current study was malnutrition, which represented 28.9% of the total inappropriate albumin indications." (PMID 35370698, 2022). "In the present meta-analysis, we found that OAGB procedures were associated with malnutrition and anemia, as well as deficiencies of blood albumin, total proteins, and calcium." (PMID 35036236, 2022). "Lymphocyte count and albumin are well-known nutritional parameters in hospitalized patients, and malnutrition is a common global cause of lymphopenia." (PMID 36059659, 2022). "Simple analyses found that age, Hb, albumin, and malnutrition were associated with 3-year mortality (p < 0.05)." (PMID 35590357, 2022). "The malnutrition of patients caused by tumors and the host response to these tumors can alter albumin levels." (PMID 35464000, 2022). "The results showed that PD patients at risk of malnutrition and malnourished group had lower uric acid, albumin, prealbumin, and total cholesterol (TC) (P < 0.05)." (PMID 35359625, 2022). "Compared with patients with a DBI score 0, those in the risk groups had a higher rate of polypharmacy, falls and malnutrition, and higher Charlson Comorbidity Score, whereas lower baseline albumin, and hemoglobin levels." (PMID 35223944, 2022). "Here, the malnutrition-obesity group was defined as patients with a BMI greater than to 30 and with either low serum albumin or significant weight loss in the last month or 6 months." (PMID 34991613, 2022). "It seems that there is an association between serum albumin, body mass index (BMI), and malnutrition." (PMID 35865866, 2022). "Based on serum level of albumin nutritional status of elderly population can be categorized as malnutrition if <3.0 g/dl, at risk if 3 to 3.5 g/dl, and well-nourished if >3.5 to 5 g/dl." (PMID 36411835, 2022). "In our results, other frailty-related parameters, including malnutrition, moderate to severe anemia (hemoglobin < 90 g/L), and severe hypoalbuminemia (albumin ≤30 g/L), were also independently associated with increased risk of POCs." (PMID 34979937, 2022). "A serum albumin level below 35 g/L is generally considered malnutrition and has been identified as a potential risk factor for poor postoperative outcomes." (PMID 35875004, 2022). "Four independent factors which represent various aspects of frailty, i.e., mFI of ≥0.27, malnutrition, hemoglobin < 90 g/L, and albumin ≤30 g/L, were combined to generate a composite risk index, each assigned with 1 point." (PMID 34979937, 2022). "Previous studies have demonstrated albumin-related malnutrition was significantly associated with poor prognosis in ESCC patients." (PMID 35241740, 2022). "Malnutrition measured by fecal fat loss and serum albumin occurred in all three intervention groups." (PMID 35858830, 2022). "Third, albumin is a marker that reflects nutritional status, and low albumin is often associated with malnutrition." (PMID 35297102, 2022). "Albumin is the main component of plasma proteins, and hypoalbuminemia reflects a malnutrition status, and cancer cachexia is caused by a sustained inflammatory response." (PMID 35846958, 2022). "In this longitudinal study, it was observed that increased anticholinergic load was associated with worsening nutritional status and decreased albumin level which is also an indirect marker for malnutrition." (PMID 35223944, 2022). "We found that malnutrition (defined as serum albumin < 36.0 g/L) modified the association between LDL-C and cardiovascular mortality (P for interaction = 0.010)." (PMID 35938138, 2022).
malnutrition (continued). "In clinical practice, serum albumin concentration has frequently been used as an indicator of malnutrition, and higher all-cause mortality was associated with lower serum albumin concentration in OSCC patients." (PMID 36230814, 2022). "Previous studies have demonstrated that malnutrition as evaluated by BMI or serum albumin level is associated with cardiovascular events in symptomatic heart failure patients." (PMID 34996387, 2022). "This hypoalbuminemia is multifactorial and caused by malnutrition, exogenous albumin loss, and volume expansion." (PMID 35837288, 2022). "Malnutrition associated with low albumin levels results in the degradation of protein and reduced muscle mass or function, i.e., strength and performance." (PMID 36551629, 2022). "Lower albumin and triglycerides levels hint at risk of malnutrition, and so the worse outcomes after transplantation." (PMID 35669472, 2022). "It is known that reduction in albumin levels is associated with the development of inflammatory conditions or malnutrition." (PMID 36195877, 2022). "We also observed that the factors associated with malnutrition were: age, Child-Pugh score, especially Child-Pugh class C, low albumin values, vitamin D deficiency, male gender, and alcoholic etiology." (PMID 35453941, 2022). "It points out that TDP related malnutrition indicators (erythrocyte, hemoglobin, serum albumin, and total protein) and FT3 are the most significant risk factors for cognitive decline in AD patients rather than other blood biochemical indicators." (PMID 35265656, 2022). "Several studies have shown that serum albumin level is associated with the outcomes of various diseases including cardio-cerebrovascular diseases, mainly due to malnutrition and inflammation." (PMID 35686040, 2022). "The malnutrition risk was assessed in terms of the presence of BMI < 23 kg/m2 or the serum albumin concentration < 38 g/L." (PMID 35057428, 2022). "It should be underlined that the mean concentration of albumin and prealbumin determinations in the group of men who died correspond to the criteria of malnutrition (PEW) according to the latest nomenclature." (PMID 36364724, 2022). "As SAM was the main component of IFIs in our study, a reduced febrile response during infection is usually associated with low serum albumin and retinol-binding protein in malnutrition." (PMID 35054490, 2022). "Albumin is the main protein produced by the liver, and it can be altered when there is liver damage, a catabolic state, malnutrition, or loss of proteins; it is also responsible for transporting numerous endogenous substances such as bilirubin." (PMID 35565913, 2022). "An elevated ASA score, obesity, and malnutrition (low levels or plasma proteins, albumin and transthyretin) were also associated to MDR-Os infection." (PMID 35304900, 2022). "Serum ALB is also produced by the liver and severe inflammatory diseases and malnutrition will cause serum ALB levels to decrease." (PMID 35372394, 2022). "The diagnostic parameters of severe malnutrition diagnosis were calculated for albumin (cutoff point—3.3 g/L) and CRP (cutoff point—32.62 mg/L)." (PMID 35276861, 2022). "Higher GLR and mGPS mean higher FBG and CRP levels, and lower lymphocyte count and albumin levels, which are associated with high inflammatory status, malnutrition and immune insufficiency." (PMID 35619963, 2022). "Serum albumin can also be used as a malnutrition marker; low levels are associated with adverse outcomes after cardiac surgery." (PMID 35745221, 2022). "The geriatric nutritional risk index (GNRI) is an indicator of malnutrition, which can be used as an uncomplicated and important factor for predicting the results achieved from only serum albumin and the rate between ideal and practical body weights." (PMID 35392884, 2022).
malnutrition (continued). "In short, our study indicates that malnutrition in patients with COVID-19, evidenced by low albumin and prealbumin levels, is associated with clinical severity parameters and inflammatory parameters." (PMID 36558522, 2022). "This group of patients appears to have a higher risk of malnutrition, and reduced albumin levels are one of the indicators of it." (PMID 36235613, 2022). "Accordingly, serum albumin as a surrogate parameter for malnutrition has been repeatedly identified as a risk factor for poor seroresponses after vaccination against SARS-CoV-2-related diseases." (PMID 35214785, 2022). "There is an association between serum albumin level and malnutrition, but it cannot be used as a nutritional marker." (PMID 35276861, 2022). "Four frailty deficits, i.e., modified frailty index ≥0.27, malnutrition, hemoglobin < 90 g/L, and albumin ≤30 g/L, were combined to generate a composite risk index." (PMID 34979937, 2022). "In particular, acute heart failure increases the risk of malnutrition due to decreased albumin production due to hepatic congestion, decreased absorption of nutrients due to intestinal edema, and decreased food intake." (PMID 36297028, 2022). "As a malnutrition and inflammation marker, a reduced albumin level is a risk factor for malignant tumors." (PMID 35250826, 2022). "Laboratory values such as low albumin and pre-albumin have been utilized as indicators of malnutrition; however, abnormalities in these values can be caused by a diverse array of pathology, including liver cirrhosis and kidney disease." (PMID 35989747, 2022). "Advanced age, low albumin level, high risk of malnutrition, high comorbidities, and transfer to ICU were significantly associated with assigning a DNR." (PMID 34433419, 2021). "Low albumin levels are a symptom of cancers, as well as liver disease, kidney disease, inflammation, and malnutrition; they are further associated with increased risk of general and cardiovascular mortality." (PMID 33639645, 2021). "Serum albumin is a reliable indicator of nutritional decline and was proven to correlate with malnutrition risk and unintentional weight loss in SSc and other chronic conditions, with our results mirroring those obtained in previous studies on the matter." (PMID 34829464, 2021). "The European Society for clinical nutrition and metabolism (ESPEN) reported that serum albumin of <3 g/dl, BMI < 18.5 kg/m2, and weight loss > 10–15% within 6 months are the best indicators of severe malnutrition in CD." (PMID 33971899, 2021). "Low body mass index (BMI) and low serum albumin levels are suggested indicators of malnutrition and are associated with poor outcomes in cancer patients." (PMID 34414685, 2021). "A score based on a combination of a diagnosis of diabetes, low calf circumference, and low serum albumin level is reported as an independent risk factor for malnutrition in COVID-19 patients." (PMID 33803339, 2021). "Several physiologic changes due to malnutrition have been implicated, including increased intestinal inflammation leading to reduced drug absorption and low plasma albumin concentrations resulting in altered protein binding." (PMID 34795281, 2021). "Cancer-related malnutrition is associated with impaired immune function and increased proinflammatory cytokine levels, and some studies have shown that lower preoperative albumin level was associated with poor prognosis." (PMID 34284775, 2021). "Reduction in albumin levels confirms the association of malnutrition with balantidiosis, as highly documented in several parasitic studies." (PMID 34627168, 2021). "Low ALB level often indicates the presence of malnutrition, which is closely related to the incidence of tuberculosis and low ALB levels have been shown to be a predictive risk factor for in-hospital mortality from tuberculosis." (PMID 34589441, 2021).
malnutrition (continued). "Body weight, body mass index, handgrip strength, skeletal muscle mass index, sum MNA score, and serum levels of albumin were lower in the malnutrition risk groups than in the normal nutrition status group." (PMID 34071812, 2021). "As an important risk factor for calciphylaxis, a significant decrease in albumin levels had been observed in calciphylaxis patients with typical malnutrition in multiple studies." (PMID 33641601, 2021). "A recent investigation in patients on hemodialysis showed that Malnutrition Inflammation Score, composite assessment of inflammation and nutritional status including serum albumin and transferrin, is associated with the response to ESA." (PMID 33863297, 2021). "But manifestations of malnutrition vary greatly among surgical patients such as body weight loss, skeleton muscle mass loss, inflammatory response, low serum albumin, and micronutrient insufficiency (i.e., vitamin D)." (PMID 34235132, 2021). "Low ALB levels, to some extent, reflect malnutrition and have been associated with poor outcomes in cancer patients." (PMID 34834417, 2021). "Although bromocresol green is a classical method for predicting serum albumin level, the use of bromocresol purple or immunologic method should be preferred to measure the serum albumin level to avoid overestimation in patient at a risk of malnutrition." (PMID 34293044, 2021). "The results indicated that if only the albumin index was used to assess the nutritional status of cancer patients, fewer patients would be at risk of malnutrition." (PMID 33800823, 2021). "Protein energy wasting is closely associated with malnutrition, inflammation and arteriosclerosis and serum albumin is an established surrogate biomarker." (PMID 34620096, 2021). "For example, serum albumin levels are drastically decreased during inflammation and malnutrition, which was associated with the poor outcome in critically ill patients." (PMID 34710198, 2021). "In our patients, lower serum albumin concentration as well as higher age, WL, distal metastases, and neoadjuvant chemotherapy were risk factors for malnutrition measured by the NRS 2002." (PMID 34680194, 2021). "As a major component in serum protein, serum albumin was used to reveal long-standing malnutrition and was also associated with systemic inflammation." (PMID 33453722, 2021). "Serum albumin is considered to be a hallmark of both inflammation and cachexia, or possibly malnutrition." (PMID 33669609, 2021). "Low albumin levels can be caused by decreased synthesis due to malabsorption, malnutrition, or hepatic dysfunction or due to losses from ascites, nephropathy, or enteropathy." (PMID 34160237, 2021). "Patients with high malnutrition risk had the lowest albumin titers of the three MUST categories (p = 0.012)." (PMID 34829464, 2021). "Serum total cholesterol, total protein, and albumin levels were lower than the normal range, suggesting risk of malnutrition." (PMID 34328427, 2021). "Hypokalemia is used as an indicator of malnutrition, and its association with malnutrition via albumin and total protein can be estimated." (PMID 33891656, 2021). "Albumin, synthesized by the liver, is considered an important factor associated with malnutrition among patients." (PMID 33854838, 2021). "Nutritional deficiencies were found for prealbumin, albumin and transferrin at 50.5%, 23.4% and 48.5%, respectively." (PMID 34768533, 2021). "We considered the serum levels of hemoglobin and albumin (in tertiles) as the nutritional deficiency biomarkers." (PMID 35010957, 2021). "At the same time, high-risk GIST leads to severe malnutrition and even cachexia, which is characterized by a decrease in serum albumin levels." (PMID 33014783, 2020). "In fact, albumin has been always linked to the nutritional status, as it rapidly increases after feeding and has always low levels during malnutrition." (PMID 32331306, 2020).
malnutrition (continued). "The geriatric nutritional risk index (GNRI), based on serum albumin level and the current body weight/ideal body weight ratio, is useful for identifying patients with malnutrition in many clinical conditions." (PMID 33321867, 2020). "Serum ALB plays a vital role in the physiological function of macromolecules in vivo and maintains nutritional levels in organisms, leading to lower ALB levels for causing malnutrition." (PMID 33553278, 2020). "The Nutritional Risk Index (NRI), calculated based on the level of albumin, current body weight, and usual body weight, was proposed for the evaluation of malnutrition status." (PMID 33266264, 2020). "Decreased serum albumin and hemoglobin implied insufficient protein intake, which will increase the risk of malnutrition-related mortality." (PMID 33204732, 2020). "Several studies have reported associations between depression and markers of malnutrition such as poor anthropometry measures, as well as low serum albumin, creatinine, hemoglobin, and nPCR levels with increased inflammation." (PMID 33076282, 2020). "Chronic inflammatory response is associated with progressive malnutrition in cancer patients, and the Glasgow prognostic score composed of albumin and CRP based on inflammatory response is crucial for the prognosis of various tumours." (PMID 33299415, 2020). "The most common criteria or tools for diagnosis of malnutrition are low serum albumin (3 studies), low BMI (3 studies), and weight loss > 10% (3 studies), followed by SGA in 2 studies." (PMID 32384662, 2020). "Bone mineral disease abnormalities, inflammation and malnutrition (weight loss, serum albumin decrease) preceded CUA onset for 6 months." (PMID 32101140, 2020). "Tumors depend on their host for sustenance and compete with the host for nutrients such as ALB, resulting in abnormal levels of ALB and PA, which can lead to malnutrition and weight loss." (PMID 32104193, 2020). "The group of fallers had significantly lower scores of MNA-SF and lower levels of albumin, suggesting an association between falls and malnutrition in our study group." (PMID 32630725, 2020). "Malnutrition, based on low BMI and/or weight loss, was present in 38.9% of patients, whereas nutritional risk, based on albumin level and weight loss, was moderate in 49.0% and severe in 35.7% of patients." (PMID 33260603, 2020). "Serum albumin is a marker for malnutrition and is one of the factors predisposing to infection in uremic and dialysis patients." (PMID 31996157, 2020). "High globulin is found in cancer, rheumatoid diseases, and chronic liver disease, and low albumin is associated with chronic infections, malnutrition, chronic liver disease, and nephrotic syndrome." (PMID 32877465, 2020). "Although pre-albumin is mostly used as a marker of malnutrition in hospitalized or post-surgical patients, there is evidence that lower levels of pre-albumin are associated with a catabolic state while higher levels are associated with anabolic conditions." (PMID 30670838, 2020). "The MNA categorizes the older individuals in “well nourished,” “at risk of malnutrition,” or “malnourished”: in some studies, this measure has been reported as being closely associated with clinical assessment, albumin, BMI, energy intake, and vitamin status." (PMID 32336948, 2020). "By a post-hoc comparison, we found that albumin levels was significantly lower in subjects who were malnourished and at risk of malnutrition compared to those who were well-nourished according to the MNA-SF." (PMID 32183760, 2020). "Our results showed that in the HD cohort, the association was evident in overhydrated patients, with loss of RRF, manifesting signs of malnutrition and wasting, whereas the corresponding association existed in PD patients with low levels of albumin and TSF." (PMID 33511145, 2020). "Albumin deficiency with albumin level less than 35 g/L in an acutely ill patient also suggests malnutrition." (PMID 33163316, 2020).